OR52R1 (olfactory receptor family 52 subfamily R member 1)
Description:
Odorant receptor.
Synonyms: OR11-22
Tractability: Antibody: UniProt places it where antibodies can reach, with medium confidence; UniProt predicts a signal peptide or a membrane-spanning region; its Gene Ontology location is reachable by antibodies, with medium confidence.
Gene: Protein-coding gene on chromosome 11 (4,803,433 to 4,804,380, reverse strand). Ensembl gene ENSG00000279270.
Subcellular location: Cell membrane
Pathways (Reactome):
Sensory Perception: Expression and translocation of olfactory receptors
Gene Ontology:
Molecular function: olfactory receptor activity; G protein-coupled receptor activity
Biological process: detection of chemical stimulus involved in sensory perception of smell; G protein-coupled receptor signaling pathway; nervous system process
Cellular component: plasma membrane; membrane
Genetic constraint (gnomAD): Loss-of-function variants: 1 observed, 4.77 expected, observed/expected ratio (o/e) 0.21, 90% interval 0.073 to 0.99. That is too few expected variants to judge how well the gene tolerates losing a copy. Missense variants: 428 observed, 415.49 expected, observed/expected ratio (o/e) 1.03, 90% interval 0.95 to 1.12. Synonymous variants: 156 observed, 156.78 expected, observed/expected ratio (o/e) 1, 90% interval 0.87 to 1.14.
Homologues: Orthologues: chimpanzee OR52R1 (96% identical), rabbit OLFR582 (84% identical), rabbit OR52R1 (82% identical), rat Or52r1c (81% identical), mouse Or52r1 (81% identical), mouse Or52r1c (81% identical), dog OR52R1 (81% identical), mouse Or52r1b (80% identical), rat Or52r1 (80% identical), pig OR52R1 (77% identical), tropical clawed frog or52m1 (47% identical). Paralogues in human: OR52L1 (57% identical), OR52E2 (54% identical), OR52N4 (53% identical), OR52E8 (51% identical), OR52J3 (51% identical), OR52M1 (51% identical), OR52D1 (51% identical), OR52H1 (50% identical), OR52K1 (50% identical), OR52E5 (50% identical), OR52A1 (49% identical), OR52A5 (49% identical), and 39 more.
Diseases named in the same sentence as OR52R1 in open-access papers:
OR52R1 is named in the same sentence as 4 diseases in open-access papers, as found by Europe PMC text mining. Sharing a sentence is not in itself a finding about the gene and the disease.
OR52R1 shares sentences with these, for which no sentence is quoted: lung carcinoma (1 paper); lymph node metastasis (1); Malignant Tumors (1); tumor (1).